IFT20 (intraflagellar transport 20)
Description:
Part of intraflagellar transport (IFT) particles involved in ciliary process assembly. May play a role in the trafficking of ciliary membrane proteins from the Golgi complex to the cilium. Regulates the platelet-derived growth factor receptor-alpha (PDGFRA) signaling pathway. Required for protein stability of E3 ubiquitin ligases CBL and CBLB that mediate ubiquitination and internalization of PDGFRA for proper feedback inhibition of PDGFRA signaling. Essential for male fertility. Plays an important role in spermatogenesis, particularly spermiogenesis, when germ cells form flagella. May play a role in the transport of flagellar proteins ODF2 and SPAG16 to build sperm flagella and in the removal of redundant sperm cytoplasm (By similarity). Also involved in autophagy since it is required for trafficking of ATG16L and the expansion of the autophagic compartment (By similarity).
Tractability: PROTAC: ubiquitination databases record sites on it.
Gene: Protein-coding gene on chromosome 17 (28,328,319 to 28,335,489, reverse strand). Ensembl gene ENSG00000109083.
Subcellular location: Golgi apparatus, cis-Golgi network; Cytoplasm, cytoskeleton, microtubule organizing center, centrosome, centriole; Cytoplasm, cytoskeleton, cilium basal body; Cell projection, cilium; Cytoplasm, cytoskeleton; Golgi apparatus; Cytoplasmic vesicle, secretory vesicle, acrosome; Cytoplasm
Subcellular location (Human Protein Atlas): Microtubules; Primary cilium; Basal body; End piece; Flagellar centriole; Mid piece; Mitotic spindle; Principal piece
Pathways (Reactome):
Organelle biogenesis and maintenance: Intraflagellar transport
Gene Ontology:
Molecular function: protein binding; small GTPase binding; opsin binding
Biological process: cilium assembly; positive regulation of cilium assembly; protein localization to Golgi apparatus; intraciliary anterograde transport; protein localization to cilium; regulation of autophagosome assembly; regulation of cilium assembly; regulation of platelet-derived growth factor receptor-alpha signaling pathway; spermatogenesis; protein localization to ciliary membrane
Cellular component: centrosome; ciliary basal body; ciliary base; cis-Golgi network; intraciliary transport particle A; intraciliary transport particle B; photoreceptor connecting cilium; acrosomal vesicle; ciliary tip; cilium; cytoplasm; Golgi apparatus; Golgi membrane; intraciliary transport particle; manchette; neuron projection; non-motile cilium; centriole; cytoplasmic vesicle; cytoskeleton; dendrite terminus; kinociliary basal body; microvillus; motile cilium; photoreceptor outer segment; and 1 more
Genetic constraint (gnomAD): Loss-of-function variants: 1 observed, 8.96 expected, observed/expected ratio (o/e) 0.11, 90% interval 0.039 to 0.53. That is too few expected variants to judge how well the gene tolerates losing a copy. Missense variants: 114 observed, 115.42 expected, observed/expected ratio (o/e) 0.99, 90% interval 0.85 to 1.15. Synonymous variants: 37 observed, 40.44 expected, observed/expected ratio (o/e) 0.92, 90% interval 0.7 to 1.2.
Homologues: Orthologues: dog IFT20 (100% identical), guinea pig IFT20 (100% identical), macaque IFT20 (100% identical), pig IFT20 (100% identical), rabbit IFT20 (99% identical), rat Ift20 (99% identical), mouse Ift20 (98% identical), tropical clawed frog ift20 (87% identical), zebrafish ift20 (87% identical), chimpanzee IFT20 (61% identical), Caenorhabditis elegans ift-20 (34% identical), Drosophila melanogaster IFT20 (32% identical).
Diseases named in the same sentence as IFT20 in open-access papers:
IFT20 is named in the same sentence as 42 diseases in open-access papers, as found by Europe PMC text mining. Sharing a sentence is not in itself a finding about the gene and the disease. The quoted sentences say what the papers report.
ciliopathy (6 papers, 2016 to 2025). A genetic disorder of the cellular cilia or the cilia anchoring structures, the basal bodies, or of ciliary function. "Clinically, mutations or deletions of IFT20 have been linked to ciliopathies affecting the urinary, cardiovascular, skeletal, neurological, immune, reproductive, and respiratory systems." (PMID 40192002, 2025). "Impaired release of IFT20 from the Golgi and subsequent disturbance of ciliary export was recently implicated as an underlying disease mechanism in another ciliopathy with skeletal, renal, and retinal involvement." (PMID 30728324, 2019). "Our data demonstrate that IFT20 KO reduces the prevalence of primary cilia overall and on LECs, induces common ciliopathy phenotypes, and dysregulates lymphatic vessel patterning." (PMID 34055805, 2021). "Though extraciliary functions of IFT20 have been identified, IFT20 KO embryos phenocopied common developmental defects of other ciliopathy models, including hydrops/edema, polydactyly, and craniofacial abnormalities." (PMID 34055805, 2021). "However, we also described a new group of patients (group 4: GLI1+/IFT20+) expressing/re-expressing the primary cilium in a ciliopathy context." (PMID 32194829, 2020). "Here the authors identify a role for VPS15 in ciliopathy and ciliary phenotypes, and show that it interacts with GM130 and functions in IFT20-dependent cis-Golgi to cilium trafficking." (PMID 27882921, 2016). "IFT20 is involved in ciliogenesis by regulating the level and localization of other IFT proteins and may have important implications in ciliopathies and related diseases." (PMID 40192002, 2025).
breast carcinoma (5 papers, 2010 to 2022). "Taken together, we concluded that the loss of IFT20 promoted breast cancer cell migration partially by decreasing the expression of Tagln2." (PMID 33748116, 2021). "All data indicated that loss of IFT20 enhanced the migration of breast cancer cells." (PMID 33748116, 2021). "Additionally, IFT20 interacts with the actin-associated protein Tagln2, which limits cell migration and whose expression is downregulated in IFT20-deficient breast cancer cells, which may further contribute to their enhanced migration." (PMID 36292997, 2022). "Therefore, we investigated whether loss of IFT20 influenced the migratory ability of breast cancer cells." (PMID 33748116, 2021). "In mouse breast cancer cells, IFT20 inhibits epithelial mesenchymal transition and cell migration, while in human osteosarcoma and colorectal cancer cells, it promotes invadopodia formation and tumor invasiveness." (PMID 36292997, 2022). "Collectively, we concluded that loss of IFT20 caused active lamellipodia formation and induced an EMT in breast cancer cells." (PMID 33748116, 2021). "Taken together, our study has unveiled a repressor role of IFT20 in breast cancer cell migration through the cilia-independent vesicular trafficking pathway." (PMID 33748116, 2021). "In summary, we demonstrated an extraciliary and IFT-complex-independent role of IFT20, and established its function as a negative regulator of cell migration in breast cancer cells." (PMID 33748116, 2021). "In our study, knockdown of Ctnnal1 in 4T1 cells enhanced breast cancer cell migration, which was consistent with the effect of IFT20 depletion." (PMID 33748116, 2021). "Further elucidating the involvement of IFT20 in vesicle trafficking from TGN to plasma membrane will help us to better understand the role of IFT20 in breast cancer cell migration." (PMID 33748116, 2021). "Consistent with this function, loss of IFT20 in the non-ciliated mouse breast cancer cells enhances epithelial–mesenchymal transition, lamellipodia formation and cell migration." (PMID 36292997, 2022). "Using proximity-dependent biotin identification (BioID) and Strep-Tactin pulldown assays, IFT20 was found to participate in the vesicular transport of Numb and Ctnnal1 from the trans-Golgi/TGN to the plasma membrane; moreover, both IFT20 interactors inhibited breast cancer cell migration." (PMID 33748116, 2021). "Moreover, knockdown of Numb also enhanced breast cancer cell migration, which partially explained the diverse effects of IFT20 on cell migration in these cells, particularly when compared with the results in osteosarcoma and keratinocyte cells." (PMID 33748116, 2021). "Taken together, IFT20 might participate in the early metastasis of breast cancer cells, and the deletion of IFT20 enhanced the cell migratory potential." (PMID 33748116, 2021). "The consistent downregulation of IFT20 in the breast cancer cells with a manner corresponding to the malignancy potential suggests that the expression of IFT20 may be negatively correlated with breast cancer progression; this association was independent of both cilia and the classical IFT complex." (PMID 33748116, 2021). "In non-ciliated breast cancer cells, IFT20 has been reported to interact at the trans-Golgi network with two negative regulators of migration, Numb and Ctnnal1, assisting their transport to the plasma membrane." (PMID 36292997, 2022). "Using non-ciliated breast cancer epithelial cells, we discovered an important cilia-independent role of IFT20, in which it functions as a negative regulator of cell migration." (PMID 33748116, 2021). "Here, we found that knockout of IFT20 in mouse breast cancer cells lacking primary cilia promoted epithelial mesenchymal transitions (EMTs), active lamellipodia formation, and cell migration." (PMID 33748116, 2021). "Taken together, IFT20 localized at the trans-Golgi/TGN and may transport specific post-Golgi vesicles to the plasma membrane in breast cancer cells." (PMID 33748116, 2021).
breast carcinoma (continued). "Examining BT549 (breast cancer) and U2OS (osteosarcoma) cells as examples, which are also non-ciliated, we first confirmed that siRNA against either Ror2 or IFT20 also reduced the invasiveness of these tumor cells." (PMID 28127051, 2017). "We characterize five genes (TMEM97, IFT20, TNFAIP1, POLDIP2 and TMEM199) organized in a CSAGA on 17q11.2 (we term this the TNFAIP1/POLDIP2 CSAGA) and demonstrate their strong and reproducible co-regulatory transcription pattern in breast cancer tumours." (PMID 20158880, 2010). "During breast cancer progression, the occurrence of primary cilia decreases with the increasing degree of transformation, which suggests that breast cancer cells without cilia might be an appropriate model for investigating the extraciliary functions of IFT20." (PMID 33748116, 2021). "When IFT20 was depleted, these proteins could not be efficiently transported to the plasma membrane, which promoted breast cancer cell migration." (PMID 33748116, 2021). "Here, we demonstrate that knockout of IFT20 promoted non-ciliated breast cancer cell migration." (PMID 33748116, 2021).
cyst (5 papers, 2016 to 2023). A sac-like closed membranous structure that may be empty or contain fluid or amorphous material. "Consistent with our observation, inactivation of the intraflagellar transport genes Kif3a and Ift20 led to the loss of cilia, aberrant OCD, and cyst formation." (PMID 36627370, 2023). "This also applied to treatment with Forskolin, which did not induce cyst formation in Ift20−/− cells either (Fig EV3F and G)." (PMID 35695071, 2022). "To reveal whether PGE2‐dependent cyst formation relies on the presence of primary cilia, we stimulated Ift20−/− mIMCD‐3 cells, which do not form primary cilia, with PGE2." (PMID 35695071, 2022).
cystic kidney disease (5 papers, 2012 to 2025). A congenital or acquired kidney disorder characterized by the presence of renal cysts. "Two of these genes have previously shown to be associated with cystic kidney disease in mammals, namely, the genes coding for the Nek8 protein and for the intraflagellar transport protein 20 (IFT20)." (PMID 22899815, 2012). "Loss of IFT20 has been associated with cystic kidney disease and with achondroplasia." (PMID 36292997, 2022). "In mouse models, the deletion of IFT20 has been associated with retinal degeneration, impaired spermiogenesis and fertility, aberrant lymphatic vessel morphology during development and inflammation, defective opsin trafficking and photoreceptor outer segment formation, and cystic kidney disease." (PMID 40192002, 2025). "Cilia proteins KIF3A, IFT88 and IFT20, which are involved in IFT, are required for renal ciliogenesis; inactivation of each is known to cause cystic kidney disease." (PMID 23762375, 2013). "In addition, deletion of IFT20 in the mouse kidney leads to misorientation of the mitotic spindle and cystic kidney disease." (PMID 40192002, 2025). "This protein has been shown to traffic along the ciliary axoneme as part of the IFT particle, and thus IFT20 knockout inhibits cilia assembly in retinal epithelia and conditional IFT20 deletion in mouse kidney disrupts ciliogenesis and leads to cystic kidney disease." (PMID 31979260, 2020). "Analyses indicated 13 genes, in addition to Nek8 and Ift20 within this area that could potentially result in cystic kidney disease, namely: RGD1309077Phf12, Flot2, Spag5, Sdf2, Supt6h, Proca1, Traf4, Sarm1, Nlk and Ksr1." (PMID 22899815, 2012).
male infertility (5 papers, 2018 to 2024). The inability of the male to effect fertilization of an ovum after a specified period of unprotected intercourse. "Defect of Ift20 or Ttc21 could cause male infertility and MMAF, which also observed in Cep78 knockout mice and the patient with Cep78 mutation." (PMID 36756949, 2023). "Interestingly, germline specific loss of the GMAP-210 interaction partner IFT20 causes male infertility, although whether acrosome biogenesis is affected in these mice has not been determined." (PMID 31316978, 2019). "Mutations in other IFT-B gene additional to IFT74 (IFT81, IFT20, IFT27, IFT172), and in IFT-A genes (IFT140) can cause spermatogenesis defects and male infertility in mice." (PMID 37555648, 2023). "IFT20 is an important protein in IFT complex B. Conditional Ift20 knockout mice develop male infertility due to defects in spermatogenesis and it has been proposed to be important for intramanchette transport by Zhang and colleagues." (PMID 29690537, 2018).
osteosarcoma (5 papers, 2017 to 2025). A usually aggressive malignant bone-forming mesenchymal neoplasm, predominantly affecting adolescents and young adults. "The vertebrate Golgi complex comprises stacked cisternae that are laterally linked to form the Golgi ribbon; knockdown of IFT20 disrupts the ribbon structure of the Golgi and impairs the invasiveness of osteosarcoma cells." (PMID 32010685, 2019). "Of note, IFT20 also regulates the intra-Golgi transport of surface-exposed membrane type 1-matrix metalloproteinase (MT1-MMP) in human osteosarcoma cells." (PMID 36292997, 2022). "IFT20 controls lysosome maturation by regulating the retrograde transport of cation-independent mannose-6-phosphate receptors (CI-M6PR); additionally, it affects osteosarcoma cell migration by regulating the dynamics of Golgi-associated microtubules." (PMID 33748116, 2021). "Recently, a study in human osteosarcoma cell lines (SaOS2) lacking cilia revealed that IFT20 is a new component for Ror-Wnt5a signaling and that it regulates the nucleation of Golgi-derived microtubules via interaction with the GM130-AKAP450 complex." (PMID 32010685, 2019).
retinal degeneration (4 papers, 2020 to 2025). Degeneration of the retina. "Here, we demonstrate that ablation of cilia due to loss of IFT20 in the RPE leads to defects in RPE homeostasis and functionality, ultimately leading to retinal degeneration along with visual impairment." (PMID 38048369, 2023). "Stx3 accumulates in the outer segment in models of retinal degeneration caused by defects in the BBSome, but not in Ift20 and Ift172 knockouts." (PMID 39871753, 2025). "Interestingly, deletion of IFT20 in mouse retinal pigment epithelium leads to retinal degeneration, which coincides with the transport of the ciliary membrane protein, polycystin‐2, or dynein, from the Golgi apparatus to the cilium." (PMID 40192002, 2025). "In summary, we could demonstrate that loss of IFT20 ablates cilia in the RPE and leads to a pathogenic phenotype that has a significant impact on retinal degeneration leading to visual impairment." (PMID 38048369, 2023).
polycystic kidney disease (3 papers, 2011 to 2019). A usually autosomal dominant and less frequently autosomal recessive genetic disorder characterized by the presence of numerous cysts in the kidneys leading to end-stage renal failure. "IFT20 is a ciliary protein known to be trafficked to cilia on vesicles, andknockout of IFT20 leads to polycystic kidney disease in mice.Interestingly, IFT20 has been shown to be important for polycystin-2localization to the primary cilium." (PMID 21490950, 2011). "Thus, deleting of cilia assembly gene IFT20 prevented cilia formation and promoted rapid postnatal cystogenesis, while disturbed IFT resulted in a variety of disorders, including polycystic kidney disease." (PMID 24397250, 2014).
colorectal cancer (2 papers, 2022). A primary or metastatic malignant neoplasm that affects the colon or rectum. "A new study found that IFT20 promotes collective invasion of colorectal cancer by regulating organization of Golgi-associated, stabilized microtubules and Golgi polarity in colorectal cancer cells at the invasive front." (PMID 35869490, 2022). "Down-regulated expression of IFT20 mRNA or protein could not only inhibit ciliary assembly and decrease the quantity of primary cilia in mammalian cells, but also reduce invasion and metastasis of colorectal cancer and osteosarcoma cells." (PMID 35869490, 2022).